RBM20 (RNA binding motif protein 20)
Diseases named in the same sentence as RBM20 in open-access papers (continued):
Sharing a sentence is not in itself a finding about the gene and the disease.
heart failure (continued). "The predicted targets of miR-532-5p were Med1, NFATfatc1, and RBM20, which were reported to play crucial roles in the pathogenesis of heart failure." (PMID 29147650, 2017). "This affected many known genes and biological processes involved in DCM (e.g., TBX20, RBM20) or heart failure (NPPA, NPPB) and also revealed many novel DCM candidate genes." (PMID 28903782, 2017). "Diastolic dysfunction is an important contributor to the pathophysiology of heart failure, and our recent identification of RBM20 as a titin splice factor has provided a unique target to adjust the diastolic properties of the heart." (PMID 27889803, 2016). "The current goals were to understand how the Rbm20-/- rat is related to physiological, structural, and molecular changes leading to heart failure." (PMID 24367651, 2013). "Patients with DCM who carry pathogenic variants in the LMNA, RBM20, and DSP genes are at higher risk for heart failure progression and may require heart transplantation." (PMID 38999368, 2024). "The validation of RBM20 as a therapeutic target in heart failure, combined with our published RBM20 splice reporter assay, could provide a suitable basis for the future development of splice inhibitors to improve diastolic function." (PMID 27889803, 2016). "Interestingly, almost all stress and heart failure related genes in the Rbm20-/-rat are up-regulated." (PMID 24367651, 2013). "In heart failure and cardiomyopathy, RBPMS cooperates with RBM20 to regulate splicing of sarcomeric genes such as TTN, safeguarding contractile integrity, while DDX5 maintains calcium homeostasis through CAMK2D splicing, and loss of QKI results in profound sarcomere disarray and heart failure." (PMID 41399527, 2025). "Like mice lacking the RRM, mice homozygous for the I536T variant display marked alterations in the splicing of well-established RBM20 target genes but develop neither cardiac dysfunction nor heart failure." (PMID 39773891, 2025). "To illustrate, even homozygous Rbm20 KO rats do not exhibit signs of systolic dysfunction and approximately 83% of rats live over 18 months without developing heart failure." (PMID 39773891, 2025). "Importantly, we found that SLM2 but not RBM20 was regulated in the setting of heart failure in humans." (PMID 34273561, 2022). "Previous studies have determined heart-specific RBPs (RBM20, RBM24, HuR, etc.)that were not included in our heart failure-specific RBPs." (PMID 36313471, 2022). "However, here we detect distinct myocardial transcriptomic profiles in patients affected with different genetic cardiomyopathies in refractory heart failure (stage D) stratified by the affected genes (LMNA, PKP2, RBM20 and TTN) and not based on the clinical phenotype (DCM or ARVC)." (PMID 33260757, 2020).
Arrhythmia (16 papers, 2019 to 2025). Any cardiac rhythm other than the normal sinus rhythm. "Patients with DCM carrying variants of LMNA, PLN, FLNC, and RBM20 have an increased risk of developing arrhythmias." (PMID 39959410, 2025). "Human patients with RBM20 variants are susceptible to arrhythmias such as ventricular tachycardia, leading to cardiac transplantation, implantation of an implantable cardioverter-defibrillator, or sudden death." (PMID 36198914, 2022). "RBM20 variants lead to arrhythmia; therefore, early ICD implantation and antiarrhythmic drug therapy can be an option for treatment." (PMID 34021826, 2021). "We immediately recognized that the phenotype in Rbm20 knockout (KO) rats resembled, at least in some respects, that previously reported in individuals with DCM caused by pathogenic genetic variants in RBM20 with cardiac remodeling, increased susceptibility to arrhythmia, and premature mortality." (PMID 39773891, 2025). "Depletion and mutations of Rbm20 in rodent and pig models have also shown severe DCM and arrhythmias." (PMID 34523260, 2021). "For individuals with DCM and a pathogenic/likely pathogenic variant in a gene correlated with life-threatening arrhythmias (LMNA, FLNC, RBM20, DSP), exercise should be restricted to recreational activities." (PMID 33040239, 2020). "Although, in both the mutant and knockout model, splicing activity of RBM20 targets was affected, there are several examples, where the mutant leads to an altered calcium handling and subsequently to arrhythmia, while homo- and heterozygous knockouts showed regular cardiac electrical activity." (PMID 34575212, 2021). "In summary, RBM20 remains an intriguing target to therapeutically change titin (and thereby cardiac) compliance; however, potential side effects of RBM20 inhibition, including the potential induction of arrhythmias, cannot be neglected." (PMID 32789749, 2020). "This Rbm20 KO mouse model exactly phenocopies our KO rat model by which the Rbm20 KO mice increase the expression of larger titin isoform, develop DCM and exhibit arrhythmias." (PMID 34523260, 2021). "In mice, mutations in RBM20 are associated with signs of arrhythmia, unlike knockout models, where the reduced or eliminated expression of RBM20 resulted in a less severe phenotype, exemplified by the comparison of homozygous RBM20-p.Ser637Ala mutants with the complete knockout of RBM20." (PMID 34575212, 2021). "LMNA and SCN5A have long known to be associated with life-threatening ventricular arrhythmias, and the studies of RBM20, DSP, and FLNC discussed here clearly demonstrate significant arrhythmia and sudden death risks." (PMID 33040239, 2020). "Unlike rodents with Rbm20 ablation, these genetic variant KI animals developed severe DCM with cardiac dysfunction and arrhythmia, even in heterozygous carriers, mirroring disease in human patients." (PMID 39773891, 2025). "In addition, RBM20, as a splicing repressor, may have a similar mechanism in high expression in HCM and inherited arrhythmias in pediatric populations, warranting further exploration of its link between the two diseases." (PMID 38994496, 2024).
Ventricular arrhythmia (14 papers, 2018 to 2025). "Ventricular arrhythmias caused by RBM20-associated abnormal splicing of ion channels genes such as RYR2 were also reported." (PMID 36198914, 2022). "However, patients that carry a pathogenic RBM20 mutation have more ventricular arrhythmias comparing to patients with a TTN mutation." (PMID 35783855, 2022). "DCM patients with RBM20 mutations have been reported to present with more severe cardiac phenotypes, including impaired cardiac function, atrial fibrillation (AF), and ventricular arrhythmias leading to sudden cardiac death, compared to those with mutations in the other genes." (PMID 33110103, 2020). "Furthermore, genetic testing has identified other DCM-causing genes including filamin C (FLNC) and RBM20 which may be associated with higher rates of ventricular arrhythmia." (PMID 31768884, 2019). "Mutations in genes such as LMNA, PLN, RBM20, and FLNC are associated with an increased risk of ventricular arrhythmias (VA) and SCD." (PMID 40711538, 2025). "Mutations in the actin-binding protein, filamin C, and RNA-binding motif protein 20 (RBM20) have been identified in 1%–5% of all DCM cases with a severe phenotype and often associated with ventricular arrhythmias and sudden cardiac death." (PMID 39772618, 2025). "Recently, RBM20 (OMIM: 613171), a gene encoding RNA-binding motif protein 20, has also been identified as a high-risk gene associated with ventricular arrhythmias." (PMID 39941414, 2025). "Of the patients with diagnostic variants, 15.8% (81/514) had a variant in genes that have been associated with increased risk of ventricular arrhythmias (LMNA, RBM20, FLNC, and PLN)." (PMID 37795486, 2023). "An independent study of 15 Dutch families with RBM20 pathogenic variants, all within the exon 9 and exon 11 enriched regions, found 66% penetrance of DCM and 30% with significant ventricular arrhythmia or sudden death." (PMID 33040239, 2020). "Here, we show that Rbm20 mutant mice harboring a missense mutation S637A in the RSRSP stretch, mimicking that in a DCM patient, demonstrated severe cardiac dysfunction and spontaneous AF and ventricular arrhythmias mimicking the clinical state in patients." (PMID 33110103, 2020). "We found that the Rbm20 mutant mice harboring a missense mutation in the RSRSP stretch mimicking a mutation in a patient with DCM, showed severe cardiac dysfunction with atrial and ventricular arrhythmias, mimicking clinical patients." (PMID 33110103, 2020). "Ventricular arrhythmia has not been reported for the ΔRRM or KO mouse models, and therefore another animal model that phenocopies the RBM20-linked DCM is awaited." (PMID 30547036, 2018).
familial dilated cardiomyopathy (10 papers, 2018 to 2025). A a genetic form of heart disease that occurs when heart (cardiac) muscle becomes thin and weakened in at least one chamber of the heart, causing the open area of the chamber to become enlarged (dilated). "Autosomal dominant mutations of RBM20 comprise 2–6% of patients with familial dilated cardiomyopathy (DCM)." (PMID 40905915, 2025). "Mutations in Rbm20 have been observed in at least 2–3% of familial dilated cardiomyopathy (DCM) cases." (PMID 34745373, 2021). "Nearly 40 potentially deleterious variants in RBM20 have been reported in the last ten years, being found to be associated with highly arrhythmogenic events in familial dilated cardiomyopathy." (PMID 33671899, 2021). "RBM20 is highly expressed in the heart and mutations in RBM20 cause familial dilated cardiomyopathy (DCM) by promoting the expression of a long isoform of the sarcomere protein titin." (PMID 31717392, 2019). "Mutation in RBM20 is linked to autosomal-dominant familial dilated cardiomyopathy (DCM), yet most of the RBM20 missense mutations in familial and sporadic cases were mapped to an RSRSP stretch in an arginine/serine-rich region of which function remains unknown." (PMID 29895960, 2018).
hypertrophic cardiomyopathy (9 papers, 2018 to 2025). "Particularly relevant are circRNAs originating from the multi-exon gene Titin, that are dysregulated in both dilated and hypertrophic cardiomyopathies, and are regulated by the splicing factor RNA binding motif protein 20 (RBM20)." (PMID 33129318, 2020). "In hypertrophic cardiomyopathy (HCM), MYBPC3, MYH7, PRKAG2, RAF1, and RBM20 were prevalent." (PMID 41341110, 2025).
cardiac hypertrophy (7 papers, 2016 to 2025). "In Ang II‐treated Rbm20 KO rats, this decrease was blunted, indicating a reduction in Ang II‐induced cardiac hypertrophy in these animals." (PMID 40119572, 2025). "Similar to siRNA knockdown, a significant reduction of RBM20 has been previously measured in cardiomyocytes treated with neurohumoral factors known to stimulate cardiac hypertrophy." (PMID 31717392, 2019). "Furthermore, we show that the reduced arterial stiffness in Rbm20 KO rats lessens Ang II‐induced cardiac hypertrophy and fibrosis." (PMID 40119572, 2025). "This improvement could result from a direct effect of the differential splicing of RBM20 substrates that relate to cardiac hypertrophy signaling." (PMID 27889803, 2016). "Thus, the reversion of diastolic dysfunction and cardiac atrophy in N2B-KO mice by reduced expression of functional RBM20 is dependent on titin’s mechanical properties and associated with a posttranscriptional effect on FHL1, which links titin-based biomechanics to cardiac hypertrophy signaling." (PMID 27889803, 2016). "It is reasonable to speculate that the cooperatively regulating RBM20 and RBM24 may affect myocardial stiffness, because cardiac hypertrophy is closely related to wall stiffness and compliance, but the mechanisms remain unknown." (PMID 35783855, 2022). "Although Rbm20 or Rbm24 individually display weak or no activity on Enh splicing, they cooperate to promote expression of the Enh3 and Enh4 isoforms of Enh, which lack the LIM domain and function to repress cardiac hypertrophy." (PMID 38535111, 2024). "In addition, promoting RBM20 and RBM24 increased the expression of ENH subtypes lacking LIM domains (such as ENH3 and ENH4), thus prevented myocardial hypertrophy in mice." (PMID 35783855, 2022).
familial cardiomyopathy (6 papers, 2017 to 2024). An instance of cardiomyopathy that is caused by an inherited modification of the individual's genome. "Hence, loss-of-function mutations in human RBM20 have previously been shown to cause hereditary cardiomyopathy due to impaired Titin isoform transition and excessive production of the N2BA isoform in the RBM20-deficient hearts leading to weak Titin filaments and replacement fibrosis." (PMID 36675070, 2023). "RBM20 plays a role in the familial cardiomyopathy acting on titin and tropomyosin, two proteins involved in the biomechanics of the striated muscle." (PMID 35027621, 2022). "RNA-binding motif protein 20 (RBM20) is a well-known Titin splicing repressor and a gene for hereditary cardiomyopathy." (PMID 29186814, 2017).
atrial fibrillation (5 papers, 2017 to 2021). A disorder characterized by an electrocardiographic finding of a supraventricular arrhythmia characterized by the replacement of consistent P waves by rapid oscillations or fibrillatory waves that vary in size, shape and timing and are accompanied by an irregular ventricular response. "A recent large-scale genome-wide association study (GWAS) of >1 million people including 60,620 atrial fibrillation cases have identified RBM20 as one of genes near risk variants, suggesting its implication in atrial cardiomyopathy." (PMID 30547036, 2018). "Novel variants in DCTN1, MYH14, and RBM20 were identified in Family 1 with cardiac and limb-girdle muscle involvement and in TRIM63, ACTC1, and TTN in the proband of family 2 with a distal lower limb phenotype and atrial fibrillation." (PMID 33170376, 2021). "Three of eight subjects carrying RBM20 alterations (37.5%) had atrial fibrillation (AF), whereas 19 subjects without rare pathogenic alterations (7.4%) had AF (p = 0.02)." (PMID 33671899, 2021). "RBM20 is also likely to be an important regulator of the pulmonary myocardium molecular phenotype, is associated with NKX2-5 expression, and could be an important therapeutic target in atrial fibrillation." (PMID 28720711, 2017).
ischemic heart disease (4 papers, 2018 to 2021). "It is a direct target of RBM20, an alternative-splicing regulator of cardiac genes which is associated with coronary heart disease." (PMID 31010208, 2019). "Another interesting observation is that the N2BA TTN isoform normally repressed by RBM20 is upregulated in ischemic heart disease and in dilated cardiomyopathy." (PMID 30948719, 2019).
arrhythmogenic right ventricular cardiomyopathy (3 papers, 2021 to 2025). "Later, RBM20 mutations were also described in association with arrhythmogenic right ventricular cardiomyopathy and left ventricular noncompaction cardiomyopathy." (PMID 33450993, 2021).
sudden cardiac arrest (3 papers, 2021 to 2024). Unexpected rapid natural death due to cardiovascular collapse within one hour of initial symptoms. "Patients with RBM20 variants exhibited a higher prevalence of sudden cardiac arrest (6.7% vs. 0.9%, p = 0.001) and increased SCD risk factor counts." (PMID 39507141, 2024). "Its mechanism may involve the 12 rare deleterious variants present in RBM20, which may play a role in causing protein dysfunction and increasing the risk of sudden cardiac arrest (SCA) in HCM." (PMID 38994496, 2024). "GT identified RBM20 variants in 2.4% of HCM patients, linked to higher sudden cardiac arrest prevalence, improving risk stratification and personalized management." (PMID 39507141, 2024).
diabetes (2 papers, 2019 to 2024). "A recent study indicates a potential role for RBM20 in cardiovascular complications of diabetes by mediating insulin damage in cardiac tissues." (PMID 38664626, 2024).
diastolic heart failure (2 papers, 2018 to 2020). Heart failure caused by abnormal myocardial relaxation during diastole leading to defective cardiac filling. "These analyses identified cardenolides as inhibitors of RBM20-mediated titin splicing, opening the possibility to treat diastolic heart failure by modulating titin splicing through drugs targeting RBM20." (PMID 32276354, 2020). "Nevertheless, it failed to improve cardiac function in patients.Accordingly, we chose titin directed alternative splicing as our therapeutic target for diastolic heart failure and developed a cell based assay to identify small molecules that inhibit the recently identified titin splice factor RBM20." (PMID 29889873, 2018).
Left ventricular dilatation (2 papers, 2013 to 2021). Enlargement of the chamber of the left heart ventricle. "Defective splicing that is caused by the RBM20 mutation in rats resulted in features resembling those of humans carrying RBM20 mutations, including left ventricular dilatation, subendocardial fibrosis, arrhythmia, and sudden death." (PMID 33671899, 2021). "Heterozygous and homozygous Rbm20-/- rat hearts had left ventricular dilatation, an increased percentage of sudden death, and increased fibrosis." (PMID 24367651, 2013).
left ventricular non-compaction cardiomyopathy (2 papers, 2021 to 2024). "Although there are several reports of nonsense or frameshift variants in RBM20 associated with DCM or left ventricular non-compaction cardiomyopathy (LVNC), the pathomechanism of these mutations remains unclear." (PMID 34201072, 2021).
myocardial disease (2 papers, 2018 to 2022). "RNA-binding motif protein 20 (RBM20), which is an important pathogenic gene of myocardial disease, is dependent on TTNcircRNAs and targets multiple key cardiac genes, such as calcium/calmodulin-dependent kinase II (CAMK2D), while also being dependent on titin (TTN) circRNAs." (PMID 35269870, 2022).
myotonic dystrophy type 1 (2 papers, 2022 to 2025). Steinert disease, also known as myotonic dystrophy type 1, is a muscle disease characterized by myotonia and by multiorgan damage that combines various degrees of muscle weakness, arrhythmia and/or cardiac conduction disorders, cataract, endocrine damage, sleep disorders and baldness. "For example, RNA sequencing of a sudden death patient revealed an abnormal LDB3 splicing pattern, which is linked to myotonic dystrophy type 1 (DM1), whereas previously performed clinical exome sequencing had identified a variant in RBM20 of unclear significance." (PMID 39982482, 2025).
amyotrophic lateral sclerosis (1 paper, 2021). Amyotrophic lateral sclerosis (ALS) is a neurodegenerative disease characterized by progressive muscular paralysis reflecting degeneration of motor neurons in the primary motor cortex, corticospinal tracts, brainstem and spinal cord. "Analysis of RBM20 RNA binding by eCLIP reveals a gain-of-function preference of mutant RBM20 for 3′ UTR sequences that are shared with amyotrophic lateral sclerosis (ALS) and processing-body associated RNA binding proteins (FUS, DDX6)." (PMID 34732726, 2021).
atrioventricular block (1 paper, 2024). A heart block that is initiated in the atrioventricular node. "DCM patients with mutations in LMNA, PLN, RBM20, FLNC, DES, or SCN5A are associated with typical cardiac rhythm disorders ranging from atrioventricular blocks to supraventricular and malignant ventricular arrhythmias (MVA)." (PMID 39070560, 2024).
Atrophy (1 paper, 2016). Any weakening or degeneration, especially through lack of use. "A ~50 % reduction of RBM20 activity does not only maintain cardiac filling in diastole but also ameliorates cardiac atrophy and thus improves cardiac function in the N2B-deficient heart." (PMID 27889803, 2016).